INSM1 (INSM transcriptional repressor 1)
Diseases named in the same sentence as INSM1 in open-access papers (continued):
Sharing a sentence is not in itself a finding about the gene and the disease.
tumor (continued). "In our case, immunostaining showed positive results for CgA, Syn, CD56, SSTR2, INSM1, CK and Ki-67, consistent with the histopathologic examination, confirming the neuroendocrine nature of the tumor." (PMID 40034377, 2025). "Two studies included cases with mixed tumor types; in these, INSM1 positivity was assessed and reported separately for each component." (PMID 40805240, 2025). "INSM1 expression promotes tumor growth, NED, and aggressive malignancy, while its inhibition reduces tumorigenicity in vitro and in vivo." (PMID 41514864, 2025). "In the case presented, immunohistochemistry demonstrated solid and diffuse staining for synaptophysin and INSM1, along with a remarkably high Ki-67 proliferation index approaching 100%, thus indicating an aggressive tumor with high metastatic potential." (PMID 41333490, 2025). "In humans, neoplasms from C cells typically express calcitonin and neuroendocrine markers such as chromogranin A and INSM1, alongside variable expression of CK7." (PMID 41320889, 2025). "In NB, elevated INSM1 expression reflects a developmental arrest, maintaining tumor cells in an immature, progenitor-like state." (PMID 41514864, 2025). "Nevertheless, we leveraged our transcriptomic analyses in eNSCs to define an oncogenic INSM1 signature that exhibited upregulation in later cycling subpopulations during evolution of a human PRO GBM tumor." (PMID 41354838, 2025). "We next wanted to understand the relationship between human GBM tumor evolution and normal cortical development with regard to the INSM1 program." (PMID 41354838, 2025). "Recent evidence highlights the transcription factor INSM1 as a critical regulator in NE development and tumor biology." (PMID 41514864, 2025). "This highlights the importance of increased INSM1 expression in late PRO human GBM tumor cell evolution and suggests the emergence and hijacking of an IPC-like cell state." (PMID 41354838, 2025). "Immunohistochemistry revealed tumor cells positively expressed vimentin, Cluster of Differentiation 34 (CD34), cytokeratin (CK), and CD56, while they negatively expressed insulinoma-associated protein 1 (INSM1), S100, CD68, and so on." (PMID 41244767, 2025). "TR have been reported to be significantly associated with high‐grade tumors (Hyams‐grade III–IV), advanced tumor‐stage, expression of the biomarker INSM1, and a reduced survival time." (PMID 40344225, 2025). "INSM1 is a highly sensitive and specific single marker for neuroendocrine differentiation across all tumor types in the head and neck region." (PMID 39937015, 2025). "Retinoic acid-induced differentiation downregulated INSM1 and N-Myc, linking INSM1 to tumor cell immaturity." (PMID 41514864, 2025). "Tumor cell evolution triggers stress-related metabolic changes and transitions toward a neuronal progenitor network driven by transcription factor INSM1." (PMID 41354838, 2025). "The tumor cells were positive for GATA3, TRPS1, E-cadherin and the neuroendocrine markers Syn and insulinoma associated protein 1 (INSM1)." (PMID 40994809, 2025). "We used reference-based label transfer between the human cortical progenitor cell atlas and our PRO human GBM data to investigate the relationship between normal developmental cell types and INSM1-dependent GBM tumor dynamics." (PMID 41354838, 2025). "The tumor was 2 mm in diameter, invaded the submucosal layer, and positive for INSM1 (insulinoma-associated protein 1)." (PMID 38231465, 2024). "The immunohistochemical results showed that the tumor cells were diffuse and positive for chromogranin A (CgA), synaptophysin (Syn), and INSM1." (PMID 39518315, 2024). "Histologically, tumors from both intact and castrated mice exhibited KRT8+NKX3.1+ luminal-like regions along with SYP+INSM1+ NE tumor foci." (PMID 39024561, 2024). "Two positive-hit compounds, 5′-iodotubercidin (5′-IT) and homoharringtonine (HHT), showed potent inhibition of INSM1 promoter activity, N-Myc expression, and NB tumor cell growth." (PMID 37627018, 2023).
tumor (continued). "In contrast to the broad inhibition of NB tumor cell growth, we chose INSM1 as a prominent target for the treatment of N-Myc-activated high-risk NBs." (PMID 37627018, 2023). "The positive feed-forward-loop of INSM1 activation and enhanced N-Myc stability is essential for aggressive NB tumor growth and oncogenesis." (PMID 37627018, 2023). "The THp-N-Myc mouse tumor is strongly positive for the expression of Insm1, which can be a direct target from our selected small molecules." (PMID 37627018, 2023). "The re-expression of INSM1 in NB tumor cells contributes to the aggressive phenotype of a certain subtype of NB with enhanced N-Myc protein expression that is a well-confirmed oncogenic driver for the development of NB." (PMID 36290282, 2022). "Several chemical compounds were identified as potent inhibitors for INSM1 and N-Myc expressions, as well as readily suppressing NB tumor cell growth." (PMID 36290282, 2022). "By screening a small molecule library using INSM1 promoter-driven luciferase assay, we were able to identify multiple inhibitors potently inhibiting INSM1 promoter activity as well as NB tumor cell growth." (PMID 36290282, 2022). "Insulinoma‐associated 1 (INSM1), a highly expressed gene in several SCLC tumors, which is used as a cytoplasmic marker for neuroendocrine differentiation of tumor cells (and indirectly in SCLC tumorigenesis), was also downregulated in the three cell lines." (PMID 35263037, 2022). "This high-grade tumour features a variable expression of neuroendocrine differentiation markers, including CD56, chromogranin A, synaptophysin and insulinoma-associated protein 1 INSM1." (PMID 35805976, 2022). "The ectopic expression of INSM1 stimulates NB tumor growth in contrast to the knockdown of INSM1 that inhibits NB cell proliferation." (PMID 36290282, 2022). "Among all genes, four of them—NOTCH1, INSM1, YAP1, and NEUROD1—emerge as the most significant, being associated with both shorter disease-free interval and high tumor stage and/or risk of recurrence." (PMID 36121500, 2022). "INSM1 has emerged as a novel NB biomarker that plays a critical role in facilitating NB tumor cell development." (PMID 36290282, 2022). "We then analyzed single-cell RNA-seq data from 2 paired human SCLCs before and after cisplatin recurrence where a subpopulation of ASCL1/INSM1-low, inflammatory-high tumor cells emerged after cisplatin recurrence." (PMID 36008402, 2022). "Immunohistochemically, the tumor cells were positive for CAM5.2, CD56, NSE, chromogranin A, synaptophysin, insulinoma-associated protein 1 (INSM1), and thyroid transcription factor-1 (TTF-1) clone SPT24." (PMID 35144634, 2022). "The down regulation of INSM1 also inhibits N-Myc protein expression, which contributes to NB tumor suppression." (PMID 36290282, 2022). "Immunohistochemical analysis showed that the tumor cells are strongly positive for cytokeratin (AE1/AE3) and insulinoma-associated protein 1 (INSM-1), and scatteredly positive for chromogranin A, synaptophysin, and CD56, supporting the diagnosis." (PMID 34477164, 2021). "INSM1 was positive among all patients with NCB but was only available in only 1 of 4 tumors from patients with CB (tumor 23B which was positive for INSM1)." (PMID 34162872, 2021). "The intensity and percentage of INSM1 nuclear reactivity were similar in the tumor cell population of NETs and of NECs." (PMID 34008122, 2021). "In accordance with their NE phenotype, the tumor cells showed accessibility at the promoter for the NE marker INSM1." (PMID 34599169, 2021). "Third, the Insm1 promoter was hypermethylated in human NF-PanNETs, as is often observed for tumor suppressor genes." (PMID 30796198, 2019). "Tumor DNAs were treated with bisulfite, and methylation-specific PCR was performed to test for DNA methylation within the promoter region of the Insm1 gene." (PMID 30796198, 2019).
tumor (continued). "To determine if the expression of INSM1 or YAP1 had any clinical significance, we stained a second TMA containing 55 additional SCLC tumor samples for just INSM1 expression because its robust staining and frequent positivity made it easier to score than YAP1." (PMID 29088741, 2017). "Here, we showed that the INSM1 protein is highly over-expressed in 35 SCLC tumor tissues confirming that INSM1 is a specific and sensitive NE marker of small cell lung cancer." (PMID 27072116, 2016). "When we harvested the tumor tissues, obvious bloody clots and blood vessels (black arrow pointed) were observed around the tumors to support the nutrient supply to the tumor growth in those Ad-INSM1 and Ad-N-myc xenograft tumors (blue arrow pointed)." (PMID 26456864, 2015). "Large bruised tumor masses were observed in the mice injected with INSM1 or N-myc over-expressing cell lines." (PMID 26456864, 2015). "The BME-coated invasion assay demonstrated that INSM1 directly correlated with the invasiveness of the NB tumor cells." (PMID 26456864, 2015). "Conversely, knock down of the endogenous INSM1 gene expression in BE2-M17 cells inhibited tumor growth in the INSM1 KD group after 3 months while a tumor mass was found in the control group." (PMID 26456864, 2015). "We observed that most of the INSM1-induced tumor growth was accompanied with blood vessel growth and a bruise indicating blood accumulation at the tumor location." (PMID 26456864, 2015). "The enhanced xenograft tumor formation in vivo indicates that INSM1 is capable of promoting tumorigenesis." (PMID 26456864, 2015). "In the present study, we report that INSM1 has a critical function in stabilizing N-myc in NB tumor cells that express N-myc gene." (PMID 26456864, 2015). "Recurrences are significantly associated with an advanced tumor stage, with a reduced survival time, and with the expression of biomarkers like Hyams grade (grade III–IV) or insulinoma‐associated protein 1 (INSM1)." (PMID 40344225, 2025). "INSM1 promotes oncogenesis through transcriptional regulation and potential extranuclear functions, activating signaling pathways that favor proliferation and tumor progression over terminal differentiation." (PMID 41514864, 2025). "Based on these findings, we hypothesize that INSM1 contributes to NB aggressiveness by maintaining a NE progenitor-like state, sustaining poorly differentiated tumor populations, and activating oncogenic transcriptional programs." (PMID 41514864, 2025). "Additionally, we identified an adenosine kinase (ADK) inhibitor, 5′-iodotubercidin (5′-IT) potentially inhibits INSM1 expression and NB tumor growth." (PMID 41514864, 2025). "Understanding the transcriptional consequences of INSM1 suppression may provide insight into NB cellular plasticity and uncover novel therapeutic targets aimed at promoting tumor cell differentiation." (PMID 41514864, 2025). "Fifteen compounds were identified to inhibit INSM1 promoter activity and NB tumor cell growth." (PMID 37627018, 2023). "The aims of our study are to explore novel or repurposed small molecules effectively suppressing INSM1-promoter activity, which could lead to the down regulation of N-Myc protein and NB tumor cell growth." (PMID 37627018, 2023). "Therefore, INSM1 emerges as a critical co-player with N-Myc in facilitating NB tumor cell growth and sustaining the advanced stage of malignancy." (PMID 37627018, 2023). "The TH-MYCN mouse tumor is strongly positive for the expression of Insm1." (PMID 36290282, 2022). "Our preliminary data show that a combination of a natural compound (homoharringtonine) and an AKT1 inhibitor (A674563) that is important for N-Myc protein stability significantly reduces the expression of INSM1, N-Myc, and NB tumor cell growth (unpublished results)." (PMID 36290282, 2022). "The clinical relevance of INSM1 and N-Myc expression in NB suggests that either molecule could be a prominent target for the suppression of an NB tumor." (PMID 36290282, 2022).
tumor (continued). "Accumulating new evidence has identified that INSM1, a transcriptional regulator with a zinc-finger DNA-binding domain, may function as a cytoplasmic biomarker for neuroendocrine differentiation of tumor cells." (PMID 36544484, 2022). "The immunohistochemistry (IHC) analyses showed that tumor cells were positive for thyroid transcription factor-1 (TTF-1) and neuroendocrine markers, including chromogranin A, synaptophysin, INSM1 (insulinoma-associated protein 1), and CD56." (PMID 33352665, 2020). "We also considered the possibility that a gene linked to Insm1, and not Insm1 itself, is the actual effector of tumor type in RT2 mice." (PMID 30796198, 2019). "In addition, we noticed that while the xenograft tumor started forming, a flat bruised lesion was first found under the skin area where the Ad-INSM1 infected cells were injected." (PMID 26456864, 2015). "Thus, we demonstrated that INSM1 stimulates NB tumor cell growth through increasing the level of N-myc oncogene via increased stability." (PMID 26456864, 2015). "Further, an in vivo xenograft nude mouse tumor model revealed that INSM1 promoted NB tumorigenesis." (PMID 26456864, 2015). "Furthermore, we examined the tumorigenicity potential of INSM1 in a xenograft nude mouse tumor model." (PMID 26456864, 2015). "Immunostaining showed that the tumor was neuroendocrine, as they were positive for Chromogranin A (CgA), Synaptophysin (Syn), CD56, CK, CK7, CK8, Epithelial membrane antigen (EMA), Recombinant Somatostatin Receptor 2(SSTR2), insulinoma-associated protein 1(INSM1), KI-67 was 70 %." (PMID 40034377, 2025). "Therefore, INSM1 may represent a promising GBM-specific target that inhibits crucial cell fate transitions during tumor evolution and growth." (PMID 41354838, 2025). "Of note, the role of mouse strain on RT2 tumor formation has also been monitored, and the strain of mouse can either alter the rate of tumor formation or favor other pNEN subtypes, including creating NF pNENs, dependent on expression of genes including Insm1 and IGF2." (PMID 37568572, 2023). "We have shown that targeting INSM1 could affect N-Myc stability and inhibit NB tumor cell growth." (PMID 37627018, 2023). "Functionally, INSM1 appears to sustain the NED state, promote tumor cell proliferation, and enhance malignant potential, thereby contributing to aggressive disease phenotypes." (PMID 41514864, 2025). "To determine INSM1 expression dynamics during the evolution of PRO human GBM, we performed scRNA-seq analysis of 11,384 cells from a patient tumor with PDGFRA amplification." (PMID 41354838, 2025). "Eight genes were differentially expressed at both the mRNA and protein levels, with ASCL1, EDNRB, INSM1, SOX11, SOX4, SOX8, and SIX1 showing reduced expression in tumor tissues, and CTNNB1 showing increased expression compared with para-cancer tissues." (PMID 40771813, 2025). "By linking INSM1 expressions to maintenance of the NED state and enhanced tumor proliferation, we uncovered a previously uncharacterized mechanism contributing to NB malignancy." (PMID 41514864, 2025). "This directly correlated with the evolutionary changes in the oncogenic INSM1 signature, where the NEU tumor cells, followed closely by GPM cells, displayed the highest enrichment of the INSM1 signature, in agreement with our PRO eNSC data." (PMID 41354838, 2025). "The tumor from our patient demonstrated coexpression of epithelial markers AE1/AE3 as well as neuroendocrine markers including synaptophysin, chromogranin A, INSM1, and CD56." (PMID 40843719, 2025). "Immunohistochemical analysis showed tumor cells positive for pan-endocrine markers (synaptophysin, CD56, INSM1 and chromogranin)." (PMID 38678248, 2024). "Immunohistochemical analysis of tumor cells revealed the following results: AE1/AE3(+), TTF-1(–), p40(–), chromogranin A(–), synaptophysin(–), CD56(–), INSM1(–)." (PMID 39463789, 2024).
tumor (continued). "We propose a diagnostic strategy using highly sensitive markers including TRPS1, INSM1, and P16 expression, as well as HPV and EBER testing for identification of primary tumor sites in clinical practice." (PMID 38041048, 2023). "The demonstration of the neuroendocrine nature of the tumor requires the identification of one or more neuroendocrine markers (synaptophysin, chromogranin A, CD56, or INSM1) in at least 10% of tumor cells." (PMID 36836564, 2023). "Our results are consistent with these studies identifying ZFP36L1 as a tumor suppressor in SCLC, where it also possesses the ability to bind and downregulate mRNAs that promote SCLC neuroendocrine differentiation including INSM1 and SOX2." (PMID 36008402, 2022). "In our case, the tumor cells are strongly positive for cytokeratin (AE1/AE3) and INSM1, and scatteredly positive for chromogranin A, synaptophysin, and CD56." (PMID 34477164, 2021). "Patients with hypomethylation of PAX9, STK33, GPR150, INSM1, and EPHX3 showed a shorter survival time and a higher tumor‐related mortality." (PMID 31131446, 2019). "We next looked for differential protein expression of INSM1 and YAP1 in SCLC tumors by IHC using a discovery TMA containing 22 patient tumor specimens." (PMID 29088741, 2017). "Thus, we hypothesize that INSM1 might play a role in cell migration and tumor angiogenesis." (PMID 26456864, 2015). "An assessment of the twenty-nine enteroendocrine-related transcription factors identified that ST18, INSM1 and NKX2-2 were commonly expressed in both tumor sets." (PMID 25023465, 2014). "Immunohistochemically, the tumor cells were negative for chromogranin, synaptophysin, and INSM-1 but positive for beta-catenin, CD56, and multifocally for S100." (PMID 41869246, 2026). "While most MCC show strong staining with neuroendocrine markers, our tumor only exhibited regional focal staining for synaptophysin, INSM1, and CD56 and lacked chromogranin expression entirely." (PMID 40640075, 2025). "Immunohistochemical analysis demonstrated positive expression of CK, vimentin, and CD34 in tumor cells, with negative immunoreactivity for INSM1, S100, and CD68—findings consistent with the established pathological diagnostic criteria for ES." (PMID 41244767, 2025). "In the current study, 5′-IT suppresses INSM1 promoter activity, shifts intra-/extra-cellular adenosine levels, induces adenosine receptor A3 (ARA3) signaling pathway, and triggers an apoptotic state in NB tumor cells." (PMID 41514864, 2025). "Furthermore, immunohistochemistry remains indispensable for establishing a definitive diagnosis and tumor grading, with markers such as CD117, INSM1, and Ki‐67 providing critical prognostic information." (PMID 41394933, 2025). "The tumor cells expressed CD99, synaptophysin, CD56, MUC4, and EMA (focal), but not AE1/AE3, S100, smooth muscle actin, desmin, CD34, chromogranin A, GFAP, NKX2-2, PAX7, and INSM1." (PMID 39249507, 2024). "The tumor cells showed patchy staining for INSM1 and synaptophysin, but were negative for AE1/AE3, CAM5.2, p40, chromogranin, S100, HMB45, NKX2.2, desmin, CD45 (LCA), CD3, and CD20, with intact INI1 and BRG1 expression." (PMID 39404971, 2024). "By IHC, the tumor cells in this dural region were positive for AR (diffuse) and PD-L1 (patchy, tumor proportion score 5%) without significant reactivity to INSM1 and CHGA." (PMID 39349591, 2024). "Consistent with our data above, ZFP36L1 was expressed in the inflammatory tumor cell subpopulation that emerged after cisplatin recurrence while its expression was largely absent in the ASCL1/INSM1-high neuroendocrine populations." (PMID 36008402, 2022). "Tumor cells are usually negative for cytokeratin, epithelial membrane antigen, synaptophysin, chromogranin, INSM1, inhibin, calretinin, and SF1." (PMID 36428715, 2022).